KDM5A (lysine demethylase 5A)
Diseases named in the same sentence as KDM5A in open-access papers (continued):
Sharing a sentence is not in itself a finding about the gene and the disease.
cancer (continued). "Herein, we summarize the pivotal roles of KDM5A in cancer progression, advances of research on KDM5A inhibitors and their screening methods, and the prospect of the cancer therapy by KDM5A inhibition." (PMID 33596982, 2021). "In triple-negative breast cancer (TNBC), inhibition of KDM5A resulted in anti-cancer activity via impairing cell cycle and senescence by regulating p16 and p27." (PMID 33596982, 2021). "In this review, we summarize the roles of KDM5A in human cancers, survey the field of KDM5A inhibitors including their anticancer activity and modes of action, and the current challenges and potential opportunities of this field." (PMID 33596982, 2021). "Previous studies showed that histone demethylase KDM5A can increase the proliferation and metastasis of several cancers." (PMID 33436536, 2021). "Treatment of cancer cells with 38 inhibited removal of H3K4me3, and the inhibition of proliferation was especially effective against cells expressing higher levels of KDM5A." (PMID 33596982, 2021). "Emerging studies indicate that KDM5A is responsible for driving multiple human diseases, particularly cancers." (PMID 33596982, 2021). "RT-qPCR, Western blots and immunohistochemistry revealed that the mRNA and protein expression levels of KDM5A were increased in cancer tissues compared to the adjacent normal tissues collected from the 78 PCa patients (p < 0.05)." (PMID 33087165, 2020). "KDM5A is a multidomain protein, capable of exerting both activating and repressive effects on gene expression in normal and cancer cells." (PMID 33196691, 2020). "KDM5A has recently been found to be upregulated in expression and disease-promoting in a number of other cancers, through both pro-growth and pro-metastatic effects (as recently reviewed)." (PMID 33196691, 2020). "We have shown that NGFR expression is indeed induced by multiple stress factors such as drug exposure, hypoxia and glucose starvation in multiple cancer types 45, 63 and correlates with KDM5A/B expression." (PMID 32483452, 2020). "Histone demethylase KDM5A removes methyl marks from lysine 4 of histone H3 and is often overexpressed in cancer." (PMID 30626866, 2019). "Meanwhile, derivatives of 3-thio-1,2,4-triazole (YUKA1 and YUKA2) were cytotoxic against several cancer cell lines with aberrant KDM5A expression." (PMID 30650517, 2019). "As a cancer-promoting gene, KDM5A also are reported demethylase-dependently inhibits tumor suppressor genes such as p27 and p16, and thus impairs proliferation of cancer cells via inducing cell arrest and senescence." (PMID 30650517, 2019). "Similar to KDM5A, elevated expression levels have been found in various primary cancers including melanoma, breast, testicular, and ovarian cancer." (PMID 28262558, 2017). "The small molecules presented here are excellent tool compounds for further study of KDM5A's demethylase activity and its contributions to cancer." (PMID 27224921, 2016). "Knockout of KDM5A significantly slowed tumorigenesis in three different genetically engineered mouse models of cancer." (PMID 27224921, 2016). "One compound, named YUKA1, was able to increase H3K4me3 levels in human cells and selectively inhibit the proliferation of cancer cells whose growth depends on KDM5A." (PMID 27224921, 2016). "KDM5A contributes to several key steps of cancer progression including tumorigenesis, metastasis and drug tolerance and is an attractive therapeutic target." (PMID 27224921, 2016). "A histone H3K4 demethylase, lysine (K)-specific demethylase 5A (KDM5A), is involved in the cancer cell drug tolerance." (PMID 27034728, 2016). "While the role of KDM5A remains less characterized, KDM5B is specifically implicated in the survival of cancer “stem cells”." (PMID 25329053, 2014). "KDM5A, initially discovered as a retinoblastoma (RB)-binding protein, plays a critical role in cell growth, survival, angiogenesis, invasion, and migration and inhibits differentiation and senescence in cancer." (PMID 41266313, 2025).
cancer (continued). "The key finding in this case is the potential role of KDM5A, as cancer cells with elevated KDM5A expression are hypothesized to be more sensitive to chemotherapeutic drugs like etoposide, doxorubicin and cytarabine." (PMID 41561516, 2025). "Drug-resistant cancer cells exhibit high chromatin inhibition and elevated levels of KDM5A." (PMID 38681199, 2024). "It has been shown that interfering with KDM5A expression led to apoptosis, inhibited cell proliferation, and promoted the sensitivity of cancer cells to Gefitinib, accompanied by upregulation of BAX protein expression and downregulation of Bcl-2 protein expression in LUAD." (PMID 37737707, 2023). "Interestingly, overexpression of KDM5A or KDM5B is also implicated in the progression and drug resistance of several cancers (16, 54, –56)." (PMID 37722046, 2023). "We and others have previously demonstrated chromatin-associated mechanisms by which PI3K supports cancer development and antagonizes ER signaling through the modulation of the H3K4 methylation axis, inhibition of KDM5A promoter H3K4 demethylation and KMT2D/MLL4-directed enhancer H3K4 methylation." (PMID 36970726, 2022). "KDM5A has also been shown to be involved in drug resistance in cancer cells." (PMID 35805040, 2022). "KDM5A is amplified in many types of cancer, including head and neck carcinomas." (PMID 35326475, 2022). "KDM5A is involved in the emergence of the so-called DTPs in cancer." (PMID 34184733, 2021). "Given that KDM5A and KDM5B expression are often affected in human cancer, we next investigated whether KDM5A and KDM5B expression participate in the management of drug-induced replication stress." (PMID 34184733, 2021). "KDM5A can be a target to treat cancer because it triggers tumorigenesis." (PMID 34276383, 2021). "Thus, there is a pressing necessity to discover more selective KDM5A antagonists for the treatment of various types of cancers." (PMID 30650517, 2019). "Recently, upregulation of RBP2/KDM5A expression was seen as characteristic of a drug-tolerant cancer cell subpopulation, cancer stem cells, which highlights the role of RBP2 in tumors and suggests its role in the initiation and development of HCC, but its mechanism in cancer was not eluciated." (PMID 23922798, 2013). "However, in contrast to normal tissues, there was no tendency for the H3K4me3 module to be overexpressed in the same cancer samples as the KDM5A module (PCC = 0.07)." (PMID 21886846, 2011). "Yet, due to the importance of KDM5A in human cancer, it is critical to identify a gene that could be used as a readout of KDM5A activity." (PMID 21886846, 2011). "However, in cancer cells we were unable to detect correlation between KDM5A and MLL1 expression, even when only hematopoietic cell lines were considered (PCC = −0.03)." (PMID 21886846, 2011). "Additionally, KDM5A overexpression is thought to promote stress-tolerance in cancer cells." (PMID 37880235, 2023). "In addition, the nonepigenetic roles of other histone demethylase members, such as KDM5A and KDM5B, are implicated in the repair of DNA, prevention of replication stress caused by hydroxyurea (HU), and development of HU-tolerant persister cancer cells." (PMID 36982384, 2023). "However increased expression of KDM5A, B, and C enzymes is seen in a wide range of cancers." (PMID 35406676, 2022). "Thus, either KDM5A or KDM5B could fulfil the same function in cancer development/drug resistance, depending on the cell context." (PMID 34184733, 2021). "Moreover, YUKA1 impedes the outgrowth of cancer cells resistant to targeted anti-cancer therapies, demonstrating the importance of KDM5A demethylase activity in drug resistance and supporting KDM5A inhibition as a potential therapeutic strategy to prevent tumor recurrence." (PMID 27224921, 2016). "Thus, a combination of HDAC inhibitors and KDM5A inhibitors may be preferable for treatment of cancer cells with KDM5A overexpression." (PMID 21886846, 2011).
cancer (continued). "In a cancer cell, activated AKT phosphorylates both KDM5A, leading to its nuclear exclusion, and DNMT, leading to its inactivation." (PMID 40934285, 2025). "We further uncovered lysine demethylase 5 A (KDM5A), a transcriptional repressor responsible for H3K4 demethylation at tumor suppressor genes, which promotes the growth of multiple human cancer types." (PMID 40886198, 2025). "The results indicated that KDM1A and KDM5A significantly interact with HDAC1/2, which plays a critical role in cancer by regulating gene expression through histone deacetylation, thereby influencing cell proliferation, apoptosis, and metastasis." (PMID 39239542, 2024). "KDM5A and KDM5B are overexpressed in many cancers and play a role in the response to genomic damage and drug tolerance." (PMID 39000010, 2024). "The roles of KDM5C and KDM5D in malignancies are less defined, although, in contrast to KDM5A and KDM5B, it is generally reduction of these proteins that is observed in cancers, most notably renal carcinomas." (PMID 37800333, 2023). "KDM5A and KDM5B are amplified or overexpressed in a range of cancers, including breast, ovarian, skin, and lung." (PMID 36803422, 2023). "Amplified demethylases with the highest prevalence, above 10% in basal cancers, included H3K4 demethylases KDM5A from locus 12p13.33 and KDM5B from 1q32.1 and H3K9 demethylase KDM4C from 9p24.1." (PMID 37504297, 2023). "The relationship between KDM5A, KDM5B and tumorigenesis appears to be primarily oncogenic, with a range of cancers showing increased expression of either of these two paralogs." (PMID 37800333, 2023). "The KDM5A PHD1 finger regulates the catalytic activity of KDM5A, an epigenetic enzyme often misregulated in cancers." (PMID 38456036, 2023). "Recognizing these differences, we aimed to focus on comprehensively refining the roles of KDM5A and KDM5B in the context of development and cancer progression." (PMID 36509829, 2022). "Lysine demethylase 5A (KDM5A) regulates MPC1 expression, and the KDM5A–MPC1 axis is involved in regulating the mesenchymal characteristics of cancer cells during EMT." (PMID 35968507, 2022). "Both KDM5A and KDM5B have been shown to be key determinants of a dynamic, phenotypic heterogeneity in cancer, defining differentiation, proliferation and responsiveness of cell populations to therapeutic intervention." (PMID 35899196, 2022). "We also highlight both the possibility of targeting KDM5A and KDM5B to improve cancer treatment and the limitations that must be overcome to increase the efficacy of current drugs." (PMID 36509829, 2022). "Although overexpression of KDM5A and KDM5B in several cancers has been confirmed and their oncogenic pathways have been identified, some studies report on the context-dependent tumor-suppressive roles of KDM5A and KDM5B." (PMID 36509829, 2022). "Nonetheless, further studies are required to confirm the specificity of Rh(III) complex 1 on KDM5A over KDM5B, KDM5C, KDM5D, or other lysine demethylases in other cancers to fully assess their potential in cancer treatment." (PMID 36509829, 2022). "KDM5A and KDM5B play important roles in various physiological and pathological events ranging from the maintenance of homeostasis to the development of cancer." (PMID 36509829, 2022). "While it is abundantly clear that KDM5A, KDM5B, and KDM5C can be over expressed in multiple cancers, defining their individual and separate roles in oncogenesis presents a problem." (PMID 35406676, 2022). "MPC1 expression is regulated by histone lysine demethylase 5A (KDM5A), and the KDM5A-MPC1 axis promotes cancer cell progression." (PMID 34759927, 2021). "KDM5A and KDM5B histone-demethylases are overexpressed in many cancers and have been involved in drug tolerance." (PMID 34184733, 2021). "In accordance with the roles of KDM5A and KDM5B in drug resistance, 18 reduced drug-tolerance by up to 20-fold in several cancer cell models." (PMID 33596982, 2021).
cancer (continued). "Considering the central role of KDM5A and KDM5B for the development of cancer persisters 2, 3, it is very likely that the observed shift toward oxidative phosphorylation is, at least in part, necessary to supporting epigenetic remodeling." (PMID 32483452, 2020). "Lysine-specific demethylase 5A (KDM5A), known as a histone H3K4 demethylase, has recently become a promising therapeutic target for cancers due to its key roles in important cancer processes including tumorigenesis, metastasis, and drug tolerance." (PMID 33087165, 2020). "Functional analysis revealed that the upstream regulators (RICTOR, KDM5A, MAP4K4, and TRAP1) were activated due to the aberrant expression of sperm proteins in the cancer group compared to fertile men." (PMID 32942548, 2020). "In particular, KDM5A (JARID1A/RBP2) and KDM5B (JARID1B/PLU1) contribute to cancer cell proliferation, reduce the expression of tumor suppressor genes, promote the development of drug tolerance and maintain tumor initiating cells." (PMID 31060229, 2019). "In support of this possibility, KDM5A and KDM5B have been shown to interact with the NuRD complex in cancer cells." (PMID 30940185, 2019). "Surprisingly, only eight identified genes (CCND1, CDK6, CDKN2A, KDM5A, MDM2, MLL3, PPP2R1A, and RB1) are shared by UniCovEx and CovEx, and they are all NCG cancer genes." (PMID 30828525, 2019). "KDM5A and KDM5B induces the growth of cancer cells, reduces the expression of tumor suppressor genes, facilitates the acquired tolerance of cancer-fighting drugs, and maintains tumor-initiating cells." (PMID 30064416, 2018). "Previous studies, including ours, have shown that KDM5 family histone demethylases, especially KDM5A and KDM5B, are highly expressed and promote tumorigenesis in multiple cancer types." (PMID 30080846, 2018). "In the majority of samples on the cancer tissue array, we found upregulation of BRD8 when KDM5A was upregulated and downregulation when KDM5A was downregulated." (PMID 21886846, 2011). "Taken together, these findings showed that both KDM5A and KDM5B might act as protumorigenic factors in cancer, highlighting their potential as targets for therapeutic intervention." (PMID 39239542, 2024). "Nevertheless, it is not simply identified with mutations in the KDM5A or KDM5B genes, and overexpression of these genes in cancer-tumors can happen because of changes in the regulatory region or epigenetic patterns." (PMID 37107631, 2023). "Overexpression of KDM5A could promote the proliferation of LUAD cells, inhibit apoptosis, and promote the resistance of cancer cells to Gefitinib." (PMID 37737707, 2023). "A vast number of preclinical studies have shown the potential of KDM5A and KDM5B as therapeutic targets, and further investigations aiming to develop specific inhibitors for these proteins will facilitate the treatment of various diseases, including cancer." (PMID 36509829, 2022). "Mounting evidence indicates that KDM5A and KDM5B are oncogenic and overexpressed in cancer." (PMID 35805040, 2022). "Although no studies indicate differential expression of KDM5A in the mammary glands or testis, KDM5A is well known for its role in various cancers." (PMID 36509829, 2022). "Although the functional ambiguity of KDM5A and KDM5B may slow the development of effective inhibitors, their diverse functions underscore their potential as cancer biomarkers and drug targets." (PMID 36509829, 2022). "Additionally, the heterogenic roles of KDM5A and KDM5B in different cancers and developmental stages make optimization of these inhibitors difficult." (PMID 36509829, 2022). "Additionally, unveiling the molecular mechanism behind the ambiguous roles of KDM5A and KDM5B will act as a basis for the development of personalized treatment methods for patients with cancer and other diseases." (PMID 36509829, 2022).
cancer (continued). "Moreover, KDM5A and KDM5B participate in radioresistance since their depletion sensitizes cancer cells to DNA damages induced by radiation or radiomimetic compounds." (PMID 34184733, 2021). "The KDM5 subfamily (also known as JARID1 subfamily) consists of four members, KDM5A (JARID1A), KDM5B (JARID1B), KDM5C (JARID1C) and KDM5D (JARID1D) whose deregulation in various kinds of cancer has been widely documented to contribute significantly to tumor initiation and progression." (PMID 31060229, 2019). "Knockdown of KDM5A altered H3K4 methylation and increased arrest at the G1 phase, via regulating expression of cell cycle genes including p27 and p16, leading to senescence in cancer cells." (PMID 30650517, 2019). "Gene amplification of both KDM5A and KDM5B were found in various human cancers." (PMID 30080846, 2018). "Most recently, the retinoblastoma-binding protein-2, RBP2 (JARED1A, KDM5a), a histone H3 lysine 4 (H3K4, an activating modification) demethylase, was discovered in various other cancers as complexed with EZH2, and is now the subject of intense investigation for inhibitors." (PMID 28579957, 2017). "Human KDM5A and KDM5B are overexpressed in many forms of cancer." (PMID 25329053, 2014). "Unlike dysregulation of KDM5A and KDM5B that are linked to cancer, mutations in KDM5C are found in patients with syndromic and non-syndromic intellectual disability." (PMID 25329053, 2014). "While the precise role of KDM5A and KDM5B in tumor formation remains to be elucidated, recent evidence supports the interesting notion that KDM5B overexpression promotes the growth and survival of cancer “stem cells”." (PMID 25329053, 2014). "We acquired expression data for KDM5A targets and EZH2 targets from the GSK dataset and applied z-score analysis to study the significance of their combined up- or downregulation in different cancer cell lines samples." (PMID 21886846, 2011). "Besides LSD1, enzymes involved in histone lysine methyltransferases and lysine demethylases, such as SUV39H1 (KMT1A), SETDB1 (KMT1E), KDM4B, and KDM5A, have been found to be involved in the DDR, suggesting that their inhibitors have combination therapy potential with PARPi for cancer treatment." (PMID 37973845, 2023). "The overexpression of KDM5A downregulates Pten expression by removing H3K4me3 at the Pten promoter, which consequently activates the PI3K–AKT–S6K1 signaling cascade, resulting in PD-L1 accumulation and sensitization to immune checkpoint blockade in murine cancer models." (PMID 35805040, 2022). "Drugs targeting KDM5A and KDM5B could be explored as a novel approach to treating some cancers." (PMID 36509829, 2022). "Lysine-specific demethylase 5A (KDM5A/RBP2) is identified as a chromatin-modifying enzyme related to transcriptional regulation by catalyzing removal of methyl groups from methylated lysine 4 of histone H3 and this gene is observed in multiple cancers including GC." (PMID 34372882, 2021). "We investigated the effects of siRNA-mediated depletion of histone demethylase Jarid1A (KDM5A, RBP2), which demethylates transcription activating tri- and dimethylated lysine 4 at histone H3 (H3K4me3/me2), on growth characteristics and cellular response to radiation in several cancer cell lines." (PMID 27253695, 2016). "The combination of a KDM5A inhibitor and deacetylase inhibitor has been hypothesized to be effective at both inhibiting cell proliferation by counteracting the overexpression of EMSY/KDM5A/SIN3B and, at the same time, preventing cancer cell resistance to drugs." (PMID 38769556, 2024). "None of the nuclear components, KDM5A, MAML1, SKIP and CBF1 showed significant expression changes between normal and cancer tissues." (PMID 25167871, 2014). "Therefore, the new HDM/HMT gene expression signature may explain the lack of correlation between the KDM5A module and H3K4 module in cancer compared to normal tissue." (PMID 21886846, 2011).